EPB41L4A (erythrocyte membrane protein band 4.1 like 4A)
Synonyms: EPB41L4; NBL4
Tractability: Antibody: the Human Protein Atlas places it where antibodies can reach. PROTAC: ubiquitination databases record sites on it; its protein half-life has been measured.
Gene: Protein-coding gene on chromosome 5 (112,142,441 to 112,419,313, reverse strand). Ensembl gene ENSG00000129595.
Subcellular location: Cytoplasm, cytoskeleton
Subcellular location (Human Protein Atlas): Plasma membrane; Nucleoplasm
Gene Ontology:
Molecular function: cytoskeletal protein binding
Biological process: actomyosin structure organization
Cellular component: cytoskeleton
Genetic constraint (gnomAD): Loss-of-function variants: 53 observed, 52.85 expected, observed/expected ratio (o/e) 1, 90% interval 0.8 to 1.26. The upper end of that interval is the gene's LOEUF score, 1.26, which puts it in group 5 of 6, group 1 being the genes least tolerant of losing a copy. Missense variants: 602 observed, 510.97 expected, observed/expected ratio (o/e) 1.18, 90% interval 1.1 to 1.26. Synonymous variants: 205 observed, 187.48 expected, observed/expected ratio (o/e) 1.09, 90% interval 0.98 to 1.23.
Homologues: Orthologues: chimpanzee EPB41L4A (99% identical), macaque EPB41L4A (98% identical), pig EPB41L4A (96% identical), guinea pig EPB41L4A (94% identical), mouse Epb41l4a (93% identical), rat Epb41l4a (91% identical), dog EPB41L4A (85% identical), rabbit EPB41L4A (84% identical), tropical clawed frog epb41l4a (81% identical), zebrafish epb41l4a (73% identical), Drosophila melanogaster yrt (28% identical), Caenorhabditis elegans frm-2 (23% identical), and 2 more. Paralogues in human: EPB41L5 (30% identical), EPB41L4B (29% identical), EPB41L3 (25% identical), EPB41L2 (25% identical), EPB41 (24% identical), EPB41L1 (24% identical), FRMD5 (21% identical), FRMD3 (21% identical), FRMD6 (15% identical), MYLIP (14% identical).
Diseases named in the same sentence as EPB41L4A in open-access papers:
EPB41L4A is named in the same sentence as 11 diseases in open-access papers, as found by Europe PMC text mining. Sharing a sentence is not in itself a finding about the gene and the disease. The quoted sentences say what the papers report.
COVID-19 (1 paper, 2025). A disease caused by infection with severe acute respiratory syndrome coronavirus 2. "The potential role of the EPB41L4A protein itself in SARS-CoV-2 infection or COVID-19 pathogenesis remains an important question for future investigations." (PMID 41093073, 2025).
dyskeratosis congenita (1 paper, 2018). Dyskeratosis congenita (DC) is a rare ectodermal dysplasia that often presents with the classic triad of nail dysplasia, skin pigmentary changes, and oral leukoplakia associated with a high risk of bone marrow failure (BMF) and cancer. "Filtering against the public SNP/variant repositories, we identified a host of candidate genes, EPB41L4A and CTC1 associated with colon, neural/brain muscles and Dyskeratosis Congenita maladies." (PMID 29703930, 2018).
glioma (1 paper, 2022). A benign or malignant brain and spinal cord tumor that arises from glial cells (astrocytes, oligodendrocytes, ependymal cells). "The forest plot shows that EPB41L4A.AS1, GDNF.AS1, HAR1A, LINC00237, SLC25A21.AS1, SNA13.AS1, and WDFY3.AS2 are the protective factors with HR < 1, while LINC00092, LINC00265, LINC00339, LINC00665, PAXIP1.AS2, SNHG16, SNHG9 and SOCS2.AS1 are risk factors with HR>1 in glioma patients." (PMID 35273128, 2022).
multiple myeloma (1 paper, 2020). "EPB41L4A is a target gene for the Wnt/β-catenin pathway, which is closely related to the survival of multiple myeloma cells." (PMID 31942185, 2020).
neuroblastoma (1 paper, 2021). Neuroblastoma (NB) is the most common solid, extracranial childhood tumor. "And the higher expression levels of ALCAM, CACNA2D3, DST, EPB41L4A or KIF1B were associated with better prognosis of MYCN non-amplified neuroblastoma patients." (PMID 34116676, 2021). "Interestingly, high expression levels of ALCAM, CACNA2D3, DST, EPB41L4A or KIF1B were not only associated with the prognosis of MYCN non-amplified neuroblastoma patients, but also were associated with the prognosis of all neuroblastoma patients." (PMID 34116676, 2021). "Neuroblastoma patients with higher expression levels of ALCAM, CACNA2D3, DST, EPB41L4A or KIF1B had better clinical overall survival in TARGET dataset, GSE49710 dataset and GSE85047 dataset." (PMID 34116676, 2021). "The prognostic effects of age related genes ALCAM, CACNA2D3, DST, EPB41L4A and KIF1B in pediatric neuroblastoma patients were determined by Kaplan-Meier survival." (PMID 34116676, 2021). "Next, we tried to determine the associations of ALCAM, CACNA2D3, DST, EPB41L4A and KIF1B in MYCN non-amplified neuroblastoma patients." (PMID 34116676, 2021). "We found that ALCAM, CACNA2D3, DST, EPB41L4A and KIF1B were associated with the favorable prognosis of MYCN non-amplified neuroblastoma patients." (PMID 34116676, 2021). "Furthermore, using multivariate cox regression, we determined the correlations of age, ALCAM, CACNA2D3, DST, EPB41L4A or KIF1B expression in the prediction of the clinical overall survival of MYCN non-amplified neuroblastoma patients." (PMID 34116676, 2021). "MYCN non-amplified neuroblastoma patients with lower expression levels of ALCAM, CACNA2D3, DST, EPB41L4A or KIF1B were with lower overall survival in TARGET dataset, GSE49710 dataset and GSE85047 dataset." (PMID 34116676, 2021). "ALCAM, CACNA2D3, DST, EPB41L4A and KIF1B were highly expressed in MYCN non-amplified younger neuroblastoma patients." (PMID 34116676, 2021). "MYCN non-amplified neuroblastoma is a heterogeneous disease and could be divided into sub-groups based on age or the expression levels of ALCAM, CACNA2D3, DST, EPB41L4A and KIF1B." (PMID 34116676, 2021). "Moreover, the prognostic significances of ALCAM, CACNA2D3, EPB41L4A and KIF1B in MYCN non-amplified pediatric neuroblastoma were not previously reported." (PMID 34116676, 2021).
ovarian carcinoma (1 paper, 2014). A malignant neoplasm originating from the surface ovarian epithelium. "The other up-regulated genes in STOSE cells: Serpinb8, Epb41l4a, Aif1l, and Mgll have no known links to ovarian cancer." (PMID 24672774, 2014).
tumor (4 papers, 2019 to 2025). "Conversely, EPB41L4A showed increased promoter accessibility and gene expression in the Epi-H tumor clusters." (PMID 36973268, 2023). "Taken together, these data indicate that many genes distinguish tumor groups with distinct epithelial and mesenchymal features, such as WNT5B, as well as EPB41L4A and TGFBI, controlled epigenetically by an array of transcriptional factors delineated above and chromatin accessibility changes." (PMID 36973268, 2023).
EPB41L4A also shares sentences with these, for which no sentence is quoted: cancer (1 paper); myeloma (1); papillary thyroid carcinoma (1); thyroid cancer (1).